ALDH9A1 (aldehyde dehydrogenase 9 family member A1)
Description:
Converts gamma-trimethylaminobutyraldehyde into gamma-butyrobetaine with high efficiency (in vitro). Can catalyze the irreversible oxidation of a broad range of aldehydes to the corresponding acids in an NAD-dependent reaction, but with low efficiency. Catalyzes the oxidation of aldehydes arising from biogenic amines and polyamines.
Synonyms: TMABA-DH; TMABALDH; ALDH4; ALDH7; ALDH9; E3; TMABADH
Tractability: Small molecule: a structure with a bound ligand is known; it belongs to a druggable protein family. PROTAC: ubiquitination databases record sites on it; its protein half-life has been measured.
Target class: Enzyme; Oxidoreductase
Gene: Protein-coding gene on chromosome 1 (165,662,216 to 165,698,597, reverse strand). Ensembl gene ENSG00000143149.
Subcellular location: Cytoplasm, cytosol; Cytoplasm
Subcellular location (Human Protein Atlas): Cytosol
Pathways (Reactome):
Metabolism: Carnitine synthesis
Gene Ontology:
Molecular function: 4-trimethylammoniobutyraldehyde dehydrogenase activity; acetaldehyde dehydrogenase (NAD+) activity; aldehyde dehydrogenase (NAD+) activity; aminobutyraldehyde dehydrogenase (NAD+) activity; formaldehyde dehydrogenase (NAD+) activity; small molecule binding; fatty aldehyde dehydrogenase (NAD+) activity; medium-chain fatty aldehyde dehydrogenase (NAD+) activity; oxidoreductase activity; oxidoreductase activity, acting on the aldehyde or oxo group of donors, NAD or NADP as acceptor
Biological process: aldehyde metabolic process; protein homotetramerization; serotonin catabolic process; carnitine biosynthetic process
Cellular component: cytoplasm; extracellular exosome; mitochondrion; cytosol
Genetic constraint (gnomAD): Loss-of-function variants: 34 observed, 51.02 expected, observed/expected ratio (o/e) 0.67, 90% interval 0.51 to 0.89. The upper end of that interval is the gene's LOEUF score, 0.89, which puts it in group 3 of 6, group 1 being the genes least tolerant of losing a copy. Missense variants: 598 observed, 622.81 expected, observed/expected ratio (o/e) 0.96, 90% interval 0.9 to 1.03. Synonymous variants: 218 observed, 227.99 expected, observed/expected ratio (o/e) 0.96, 90% interval 0.86 to 1.07.
Homologues: Orthologues: chimpanzee ALDH9A1 (99% identical), macaque ALDH9A1 (98% identical), dog ALDH9A1 (92% identical), rat Aldh9a1 (89% identical), mouse Aldh9a1 (89% identical), guinea pig ALDH9A1 (88% identical), tropical clawed frog aldh9a1 (77% identical), zebrafish aldh9a1a.1 (70% identical), zebrafish aldh9a1a.2 (68% identical), Caenorhabditis elegans alh-11 (48% identical), Caenorhabditis elegans alh-3 (38% identical), Caenorhabditis elegans alh-1 (38% identical), and 3 more. Paralogues in human: ALDH2 (40% identical), ALDH1B1 (39% identical), ALDH1L1 (39% identical), ALDH1A2 (38% identical), ALDH1A1 (38% identical), ALDH1L2 (38% identical), ALDH8A1 (36% identical), ALDH1A3 (34% identical), ALDH5A1 (31% identical), ALDH16A1 (28% identical), ALDH6A1 (28% identical), ALDH4A1 (26% identical), and 5 more.
Diseases named in the same sentence as ALDH9A1 in open-access papers:
ALDH9A1 is named in the same sentence as 23 diseases in open-access papers, as found by Europe PMC text mining. Sharing a sentence is not in itself a finding about the gene and the disease. The quoted sentences say what the papers report.
prostate carcinoma (4 papers, 2015 to 2025). A carcinoma that arises from epithelial cells of the prostate gland. "The role of ALDH9A1 in tumors is rarely reported, with susceptibility loci of ALDH9A1 for renal cell carcinoma (RCC) and prostate cancer." (PMID 40821701, 2025). "In addition, the expression of ALDH3A2 in adenocarcinoma, ALDH7A1 in prostate cancer and glioma, and ALDH9A1 in breast cancer and thyroid cancer is also high." (PMID 36651035, 2023). "Furthermore, it has been demonstrated that ALDH4A1 and ALDH9A1 are the primary enzyme isoforms responsible for ALDEFLUOR activity in prostate cancer tissues, whereas ALDH3A2 and ALDH18A1 are the predominant enzyme isoforms in non-tumor tissues and high-grade prostate intraepithelial neoplasia." (PMID 37686694, 2023). "By analyzing six primary prostate cancer specimens and eight prostate cancer cell lines, it was indicated that ALDH isoforms with higher expression levels were ALDH3A2, ALDH4A1, ALDH7A1, ALDH9A1, and ALDH18A1." (PMID 37686694, 2023).
ovarian carcinoma (3 papers, 2019 to 2025). A malignant neoplasm originating from the surface ovarian epithelium. "Further studies are needed to understand the regulatory mechanisms of ALDH9A1 and its potential as a prognostic biomarker or therapeutic target in ovarian cancer, particularly in the context of residual disease and chemoresistance." (PMID 40771481, 2025). "Our results and those of previous studies suggest that elucidating the role of ALDH isozymes, including ALDH9A1, in cell lineage differentiation and tumor progression may provide new insights into the pathophysiology of ovarian cancer." (PMID 40771481, 2025). "ALDH1A2, ALDH1B1, and ALDH9A1 were downregulated in the ovarian cancer cells compared to the expression in HOSE cells, whereas ALDH3A1 was upregulated in the ovarian cancer cells." (PMID 31615043, 2019).
glioma (2 papers, 2021 to 2022). A benign or malignant brain and spinal cord tumor that arises from glial cells (astrocytes, oligodendrocytes, ependymal cells). "In the LGG cohort from the TCGA dataset, ALDHs including ALDH2, ALDH6A1, ALDH5A1, ALDH9A1, ALDH1A1 were upregulated in WHO grade II gliomas while the increased expression of ALDH16A1, ALDH3B1, ALDH3A2, ALDH1A2, ALDH3A1 was found in WHO III grade gliomas." (PMID 35116021, 2021).
Obesity (2 papers, 2012 to 2020). Accumulation of substantial excess body fat. "When looking at the fatty acid metabolism in obesity and uterine cancer, three miRNA-gene interactions (miR100/ALDH9A1, miR-186/ACAA2 and miR- 193b/ALDH3A2) were shared in common." (PMID 33121472, 2020). "Since endurance exercise causes activation of PPARα, these data suggest that endurance exercise was able to restore at least in part the obesity-induced disruption of PPARα function and thereby contributed to the elevated gene expression of OCTN2, ALDH9A1, and BBOX1." (PMID 23150726, 2012).
renal carcinoma (2 papers, 2015 to 2021). A carcinoma arising from the epithelium of the renal parenchyma or the renal pelvis. "ALDH3A2 mutation has been reported to cause Sjögren-Larsson syndrome and the variation of ALDH9A1 maybe a related pathogenic factor of renal cancer." (PMID 34748517, 2021). "We also made use of TCGA clear cell data to examine the frequency of mutation of ALDH9A1, MGST3, LOC440700 and TMCO1 in renal cancer." (PMID 25826619, 2015).
renal cell carcinoma (2 papers, 2024 to 2025). "ALDH9A1 exhibits the strongest correlation with renal cell carcinoma among the 7 prognostically significant ALDHs." (PMID 39039052, 2024).
central precocious puberty (1 paper, 2021). "Further to explore the role of ALDH3A2 and ALDH9A1 in central precocious puberty will be interesting." (PMID 34748517, 2021).
colorectal cancer (1 paper, 2023). A primary or metastatic malignant neoplasm that affects the colon or rectum. "Another up-regulated protein was ALDH9A1, a member of the ALDH family of proteins which are involved in aldehyde detoxification which in turn is associated with acquired chemoresistance in colorectal cancer cells." (PMID 36604765, 2023).
endometrial cancer (1 paper, 2024). Primary or metastatic malignant neoplasm involving the endometrium (mucous membrane that lines the endometrial cavity). "The proteomic profiling of endometrial cancer cell lines revealed that ECC-1 and RL95-2 shared the ALDH isoforms ALDH3A1, ALDH3A2, ALDH3B1, ALDH3B2, ALDH7A1, ALDH9A1, and ALDH18A1 in their proteome." (PMID 38893151, 2024).
Kawasaki disease (1 paper, 2019). A rare inflammatory disease characterized by an acute febrile, systemic, self-limiting, medium-vessel vasculitis primarily affecting children. "ALDH9A1 may play a role in systemic vasculitis and vasculitis-associated diseases such as Kawasaki disease known as a mucocutaneous lymph node syndrome." (PMID 30914451, 2019). "Patients’ serum with the Kawasaki disease contains significantly induced levels of anti-ALDH9A1 antibodies." (PMID 30914451, 2019).
metastatic tumor (1 paper, 2024). "Next, subcutaneous and metastatic tumor models were employed to study the role of the ALDH9A1-IQGAP2-AKT axis in vivo." (PMID 39039052, 2024).
prostate adenocarcinoma (1 paper, 2021). "Additionally, ALDH9A1 was shown to be associated with a biochemical recurrence in the Cancer Genome Atlas prostate adenocarcinoma (TCGA-PRAD) dataset." (PMID 34572930, 2021).
serous ovarian cancer (1 paper, 2025). "In this study, we observed increased levels of P49189, also known as aldehyde dehydrogenase family 9 member A1 (ALDH9A1) or 4-trimethylaminobutyraldehyde dehydrogenase, in residual tissue from patients with high-grade serous ovarian cancer (HGSOC) treated with neoadjuvant chemotherapy." (PMID 40771481, 2025).
tumor (9 papers, 2017 to 2025). "Live small animal fluorescent imaging assays showed that the knockdown of IQGAP2 abrogated suppressive impact on tumor metastasis caused by ALDH9A1 overexpression." (PMID 39039052, 2024). "Functional experiments demonstrated that the deficiency of ALDH9A1 in ccRCC promoted tumor proliferation, invasion, migration and lipid accumulation." (PMID 39039052, 2024). "We unveiled a significant association between ALDH9A1 and tumor progression, as well as a linkage between ALDH9A1 and lipid accumulation in ccRCC." (PMID 39039052, 2024). "We established A549 cells with ALDH6A1 or ALDH9A1 depletion and found that ALDH9A1 depletion increased tumor cell death in confining pores, though its effect was weaker than that of ALDH1B1 ablation." (PMID 41390768, 2025). "Through the analyses of the promoter methylation profile derived from the ualcan website, we observed that both normal and tumor tissues exhibited extreme hypo-methylation in the promoters of ALDH9A1." (PMID 39039052, 2024). "Immunohistochemical staining demonstrated that Ki-67, the index of cellular proliferation, was declined in the tumor xenografts induced by cells with overexpression of ALDH9A1." (PMID 39039052, 2024). "The weight and volume of tumor xenografts generated by ALDH9A1-overexpression CAKI-1 cells were noticeably smaller than those generated by CAKI-1 cells bearing the empty vector." (PMID 39039052, 2024). "This study elucidated how ALDH9A1 exerted its tumor suppressor roles via the AKT-mTOR pathway in ccRCC." (PMID 39039052, 2024). "Aiming to assess the tumor suppressor role of ALDH9A1 in ccRCC in vivo, this study constructed subcutaneous tumor xenografts and tail vein metastasis models in BALB/c nude mice, with ALDH9A1-overexpressed CAKI-1 and A498 cells, respectively." (PMID 39039052, 2024). "To identify weather ALDH9A1 exerted its tumor suppressor role via the AKT-mTOR network, we administrated ALDH9A1-deficient cells with LY294002, a PI3K inhibitor." (PMID 39039052, 2024). "Taken together, these experiments supported the notion that the classical PI3K-AKT-mTOR participated in the ALDH9A1-mediated tumor-suppressor and metabolic reprogramming roles in ccRCC." (PMID 39039052, 2024). "Taken together, these results validated that ALDH9A1 exerted tumor suppressor role and metabolic reprogramming role by repressing the expression of IQGAP2 and activating the AKT-mTOR-SREBP1 pathway in ccRCC." (PMID 39039052, 2024). "To better understand the molecular mechanism of the tumor suppressor role of ALDH9A1 in ccRCC, we reanalysis the in-house transcriptome sequencing data, conducted by CAKI-1 cells overexpressing ALDH9A1." (PMID 39039052, 2024). "In this study, we have validated ALDH9A1 as a tumor suppressor gene specially in ccRCC, where its downregulation enhances tumor progression and lipid accumulation." (PMID 39039052, 2024). "The proteomics data from CPTAC further revealed a pronounced decrease in ALDH9A1 expression in ccRCC compared to other tumor types." (PMID 39039052, 2024). "While miRNA-711 potentially plays a tumor-suppressing role in PCa, its precise interaction with ALDH9A1 and the implications for tumor suppression or progression remains to be elucidated." (PMID 34572930, 2021). "Our subcutaneous tumor xenografts studies revealed that the enforced expression of ALDH9A1 remarkably restrained the tumor growth in comparisons with the vector group, whereas the knockdown of IQGAP2 reversed the impact of ALDH9A1 overexpression on the tumor growth." (PMID 39039052, 2024). "The tumor weight and tumor volume in the ALDH9A1-overexpressing group were significantly decreased, while the additional knockdown of IQGAP2 reversed this inhibition caused by ALDH9A1 overexpression." (PMID 39039052, 2024). "Here, this study revealed ALDH9A1 as a tumor suppressor gene in ccRCC." (PMID 39039052, 2024).
tumor (continued). "To further elucidate the functional significance of IQGAP2 in the tumor suppressor role of ALDH9A1 in ccRCC, we introduced shRNA to achieve stable silencing of IQGAP2 in A498 and CAKI-1 cell lines, accompanied by transfection with ALDH9A1 overexpression lentivirus or control." (PMID 39039052, 2024). "Therefore, CRISPR/Cas9 technology can be utilized therapeutically to restore ALDH9A1 expression, to slow tumor progression and achieve tumor “slimming” clinically." (PMID 39039052, 2024). "Besides, the live small animal imaging manifested that increased ALDH9A1 significantly deadened tumor metastases, and the number of metastatic nodes in the liver from the ALDH9A1-overexpressed group was less than the control group." (PMID 39039052, 2024). "The expression of MAOA, AKR1A1, ALDH9A1, HAAO, and ALDH2 was significantly downregulated in ESCC tumor tissues compared to non-tumor tissues." (PMID 40821701, 2025). "Here, we demonstrated that the attenuation of ALDH9A1 in ccRCC triggers aberrant abnormal activation of the AKT-mTOR pathway, which is responsible for the tumor progression and lipid accumulation mediated by SREBP1." (PMID 39039052, 2024). "According to the classification of normal tissues and tumor tissues, it was found that the expression of ALDH3B1, ALDH18A1, etc., increased in a variety of cancers, but ALDH9A1 and ALDH2 showed the opposite trend in UCEC." (PMID 34670872, 2021). "For example, ALDH1A2, ALDH2, ALDH3A2 and ALDH9A1 were downregulated in all tumors among the 5 cancer types, whereas ALDH1B1, ALDH1L2 and ALDH18A1 were most upregulated in tumor parts." (PMID 29426835, 2018). "While HBB is by far the most abundant transcript differentially expressed between CTCs and primary tumours, we identified 16 other antioxidant genes as being significantly upregulated, including the ALDH family members ALDH9A1 and ALDH18A1, as well as SOD1 and PRDX family members." (PMID 28181495, 2017). "The results revealed that the expression of MAOA, AKR1A1, ALDH9A1, HAAO, and ALDH2 was significantly downregulated in ESCC tumor tissues compared to non-tumor tissues." (PMID 40821701, 2025). "Thus, here we supposed that in ccRCC, the attenuation of ALDH9A1 fails to retain NPM1 in the cytoplasm and promote its accumulation in the nuclear, leading to inhibition of IQGAP2 and subsequent activation of AKT-mTOR signaling to support tumor progression and lipid accumulation." (PMID 39039052, 2024).
cancer (8 papers, 2017 to 2025). A tumor composed of atypical neoplastic, often pleomorphic cells that invade other tissues. "The isoforms aldehyde dehydrogenase 1 family member A2 (ALDH1A2), 2 family member (ALDH2), ALDH3A2, and 9 family member A1 (ALDH9A1) were downregulated in all cancers studied." (PMID 40923024, 2025). "Aldehyde dehydrogenase (ALDH1B1, ALDH2, ALDH3B1, ALDH3B2, ALDH7A1 and ALDH9A1) were involved in the resistance against cyclophosphamide/carboplatin in cancer chemotherapy." (PMID 28225065, 2017). "Interestingly, the CRISPR screen further revealed that ALDH9A1, a key enzyme that catalyzes gamma-aminobutyraldehyde to GABA, showed significant sgRNA depletion but not sgRNA enrichment in cancer cells cocultured with NK cells." (PMID 40568942, 2025).
ALDH9A1 also shares sentences with these, for which no sentence is quoted: clear cell renal cell carcinoma (1 paper); Constipation (1); epilepsy (1); liver cancer (1); opioid dependence (1); Sjögren-Larsson syndrome (1); thymoma (1); uterine cancer (1).